IL34 (interleukin 34)
Diseases named in the same sentence as IL34 in open-access papers (continued):
Sharing a sentence is not in itself a finding about the gene and the disease.
skin cancer (3 papers, 2015 to 2022). "Elevated levels of IL-34 are detectable in patients with various types of cancers, such as blood, brain, breast, eye, head and neck, lung, ovarian and skin cancer, and it has been demonstrated that IL-34 expression is associated with the progression of such tumours." (PMID 29423057, 2018). "Our detection of CSF1R and CSF1/IL34 interaction between cancer and immune infiltrating cells at the epidermal layers was consistent to the biological context of the skin cancer." (PMID 35967449, 2022). "In the present study, we firstly found that IL-34 was indeed expressed in various types of cancer, such as blood, brain, breast, colorectal, eye, head and neck, lung, ovarian and skin cancer." (PMID 25395235, 2015). "IL-34 was expressed in various types of cancer, including blood, brain, breast, colorectal, eye, head and neck, lung, ovarian and skin cancer." (PMID 25395235, 2015). "When performing a search in the PrognoScan database, the human IL-34 gene was also found to be expressed in various types of cancer, such as blood, brain, breast, colorectal, eye, head and neck, lung, ovarian and skin cancer." (PMID 25395235, 2015).
teratoma (3 papers, 2014 to 2020). A non-seminomatous germ cell tumor characterized by the presence of various tissues which correspond to the different germinal layers (endoderm, mesoderm, and ectoderm). "Therefore, targeting IL-34 and the PI3K/ERK pathways could decrease macrophage number effectively and alter the microenvironment involved in teratoma angiogenesis and development." (PMID 25071759, 2014).
ulcerative colitis (3 papers, 2019 to 2025). An inflammatory bowel disease involving the mucosal surface of the large intestine and rectum. "CSF1 and IL34 are also both induced after epithelial injury in the intestine, including in human ulcerative colitis." (PMID 40533345, 2025). "Both IL34 and CSF1 transcripts were elevated in inflamed gut tissues from Crohn's disease (CD) or ulcerative colitis (UC) patients compared to non-IBD control diverticulitis and normal tissues that were tumor-adjacent." (PMID 31552020, 2019).
vascular dementia (3 papers, 2021 to 2025). A degenerative vascular disorder affecting the brain. "However, the relationship between IL-34 and vascular dementia (VaD) has not yet been elucidated." (PMID 34095310, 2021).
Vestibular schwannoma (3 papers, 2019 to 2021). A vestibular schwannoma (also known as acoustic neuroma, acoustic neurinoma, or acoustic neurilemoma) is a benign, usually slow-growing tumor that develops from the VIIIth cranial nerve supplying the inner ear. "Macrophage colony stimulating factor and IL-34 are associated with clinical vestibular schwannoma progression." (PMID 30580386, 2019). "The authors investigated the role of tumor-associated macrophages in vestibular schwannomas by analyzing the expression of CD163, M-CSF and IL-34 in ten fast- and slow-growing vestibular schwannomas." (PMID 33530441, 2021). "Immunohistochemical expression of M-CSF and IL-34 was analyzed in ten fast-growing vestibular schwannomas and in ten slow-growing vestibular schwannomas." (PMID 30580386, 2019). "This study demonstrated the expression of M-CSF and IL-34 in vestibular schwannomas." (PMID 30580386, 2019).
acute coronary syndrome (2 papers, 2021 to 2025). Signs and symptoms related to acute ischemia of the myocardium secondary to coronary artery disease. "IL-34 knockout mouse model of myocardial ischemia/reperfusion (IR); Human acute coronary syndrome (ACS) patient samples." (PMID 40948785, 2025). "Upregulated IL-34 is also detected in human atherosclerotic plaques, particularly correlating with unstable plaques, suggesting that the pro-inflammatory activities of IL-34 in the advanced stages of plaque development may contribute to acute coronary syndrome and premature death." (PMID 34422917, 2021).
acute GVHD (2 papers, 2020 to 2024). "Finally, we assessed the suppressive function of IL-34-Tregs in vivo in a xenogeneic model of acute GVHD." (PMID 32849510, 2020). "We also analyzed the effects of IL-34 on human Treg cell generation and evaluated in immune humanized mice the suppressive function of CD8+ Tregs differentiated using IL-34-treated human monocytes in a model of acute GVHD." (PMID 32849510, 2020).
amyloid (2 papers, 2025). "In sum, Csf1 treatment, but not IL-34 application, enhances phagocytic capacity of PAM and ameliorates PAM expansion at early stages of disease, thereby facilitating restriction of amyloid pathology." (PMID 40659845, 2025).
breast tumor (2 papers, 2021). "Cell signaling activation by IL-34 also varied depending on subcellular subtype and its interaction with other receptors, suggesting that IL-34 has a differential role depending on the breast tumor subtype." (PMID 33408768, 2021). "Representative tumor images demonstrated that there was an increase in the breast tumor growth in mice treated with IL-34, as compared to those treated with phosphate buffered saline." (PMID 33800170, 2021). "We also used juglone to treat breast tumors in mice and found that juglone could decrease IL-34-induced in vivo breast tumor growth to a certain extent." (PMID 33800170, 2021). "However, the specific signaling pathway regulated by IL-34 during breast tumor development and its functions in those pathways remain to be elucidated." (PMID 33800170, 2021). "All these data suggest that IL-34 can act as an anti-tumorigenic factor in the luminal B and HER2 breast tumor subtypes, by promoting M1 macrophage differentiation, and as a pro-tumorigenic factor in basal subtypes, by promoting tumor cell migration." (PMID 33408768, 2021).
cardiac ischemia (2 papers, 2025). "IL-34 regulates the expression of proinflammatory cytokines (IL-17A, IL-1 and IL-6), which are classical cytokines involved in myocardial ischemia‒reperfusion (MI/R) injury." (PMID 39883639, 2025). "In cardiac ischemia, inflammatory cytokines such as Interleukin-34 can activate both the canonical (p65) and non-canonical (p52/RelB) NF-κB pathways within macrophages." (PMID 40948785, 2025).
cervical intraepithelial neoplasia (2 papers, 2021 to 2024). "Consistent with the mouse findings, IL34 expression was significantly reduced in high-grade cervical intraepithelial neoplasia (CIN3) and cancer, but not normal or low-grade CINs." (PMID 34805788, 2021).
cystic tumors (2 papers, 2019 to 2020). "Expression M-CSF and IL-34 were compared between fast- versus slow-growing and cystic versus non-cystic tumors." (PMID 30580386, 2019).
dementia (2 papers, 2024 to 2025). Loss of intellectual abilities interfering with an individual's social and occupational functions. "These nominated causal genetic variants are located on the IL34, CCR5AS genes and the HLA intergenic region, all of which are involved in neuroinflammatory responses relevant to dementia." (PMID 39649611, 2024).
encephalitis (2 papers, 2015 to 2019). An acute inflammatory process affecting the brain parenchyma. "The significant variability of neuronal IL-34 expression in SIV-infected animals without encephalitis may reflect other pro- or anti-inflammatory factors not investigated in this study." (PMID 25886134, 2015). "In SIV infected rhesus macaques IL-34 expression was not increased, unlike MCSF, in macrophages accumulating perivascularly and within the nodular lesions in brains with or without encephalitis." (PMID 30832693, 2019). "Here, we find that while neuronal IL-34 is significantly increased in SIVE as compared to non-infected animals and those with SIV but without encephalitis, neuronal M-CSF expression progressively decreases in SIV and SIVE." (PMID 25886134, 2015). "In contrast, bioquantification of IL-34 expression by neurons shows an overall increase in expression by animals with SIVE, as compared to those without encephalitis and non-infected animals; however, this does not reach statistical significance in this small study." (PMID 25886134, 2015). "In addition to M-CSF and IL-34 expression by cells in cerebral white matter, neurons also express both cytokines in brain of non-infected, as well as SIV-infected rhesus macaques without and with encephalitis." (PMID 25886134, 2015). "Additionally, IL-34 expression is largely unchanged from that observed in brain of non-infected animals and those with SIV infection but without encephalitis, suggesting a spatial relationship between the two cytokines in brain and, presumably, different biological roles." (PMID 25886134, 2015).
endometriosis (2 papers, 2019 to 2021). The growth of functional endometrial tissue in anatomic sites outside the uterine body. "In general, targeting the IL-34/CSF1R/JAK3/STAT6 pathway with a STAT6 inhibitor was an effective means of treating endometriosis in rats." (PMID 31727934, 2019). "We further collected the sera of endometriosis patients to confirm the changes in IL-34 expression levels." (PMID 31727934, 2019). "Ectopic ESCs were isolated and pretreated with IL-34 neutralizing antibody to validate the effects of IL-34 in endometriosis." (PMID 31727934, 2019). "First, we showed that excessive secretion of IL-34 was detected in the sera of endometriosis patients and in rat models of endometriosis." (PMID 31727934, 2019). "In conclusion, our research reveals the functional role of IL-34 in endometriosis as well as the mechanism by which IL-34 mediates its effects." (PMID 31727934, 2019). "Taken together, these results indicate that IL-34 facilitates endometriosis progression by promoting ESC proliferation, migration and invasion." (PMID 31727934, 2019). "In our present study, through reanalysis of the expression profile of IL-34 in the microarray data of the Gene Expression Omnibus (GEO) database (GSE51981), we found that IL-34 was increased in clinical samples with endometriosis." (PMID 31727934, 2019). "IL-34 expression is increased in endometriosis tissues at all stages (Minimal/Mild, Moderate/Severe), implicating the role of IL-34 in the pathogenesis of endometriosis." (PMID 31727934, 2019). "Here, the doses of IL-34 for in vitro experiments were much higher than the level of IL-34 in serum samples from endometriosis patients, which were typically less than 400 pg/mL." (PMID 31727934, 2019). "Firstly, by enzyme linked immunoabsorbent assay, we found that IL-34, VEGF, MMP-2 and MMP-9 were increased in the sera of patients with endometriosis." (PMID 31727934, 2019). "Our research reveals the function of IL-34 in endometriosis, which may provide insight into novel therapeutic strategies for endometriosis." (PMID 31727934, 2019). "This study was performed to investigate the function of IL-34 in the pathogenesis of endometriosis." (PMID 31727934, 2019). "Results demonstrated that IL-34 secretion was elevated in endometriosis patients." (PMID 31727934, 2019). "In summary, autocrine production of IL-34, mediated by STAT6, promoted the development of endometriosis in vitro and in vivo through the CSF1R/JAK3/STAT6 pathway." (PMID 31727934, 2019). "Unsurprisingly, IL-34, VEGF, MMP-2 and MMP-9 were increased in the sera of the experimental endometriosis rats, which could be abrogated by STAT6 signaling blockage with AS1517499." (PMID 31727934, 2019). "Taken together, elevated IL-34 expression may promote eutopic ESC proliferation, migration and invasion to facilitate the development of endometriosis." (PMID 31727934, 2019). "Further, an IL-34 neutralizing antibody could attenuate CSF1R/JAK3/STAT6 activation and down-regulate VEGF, MMP-2 and MMP-9, eventually leading to suppression of the development of endometriosis in vitro." (PMID 31727934, 2019). "However, the effect of IL-34 in endometriosis has not been elucidated." (PMID 31727934, 2019).
esophageal squamous cell carcinoma (2 papers, 2023 to 2025). Esophageal squamous cell carcinoma (ESCC) is a type of esophageal carcinoma (EC) that can affect any part of the esophagus, but is usually located in the upper or middle third. "Furthermore, human esophageal squamous cell carcinoma cell lines treated with 5-fluorouracil/cisplatin expressed high IL-34 and promoted induction of CD163, a marker of M2-type TAMs, in human peripheral blood monocytes." (PMID 36765929, 2023). "Along the same line are the results published by Nakajima and colleagues, who showed that neoadjuvant chemotherapy upregulates the induction of IL-34, but not CSF1, on esophageal squamous cell carcinoma cells." (PMID 36765929, 2023).
influenza (2 papers, 2021 to 2023). An acute viral infection of the respiratory tract, occurring in isolated cases, in epidemics, or in pandemics; it is caused by serologically different strains of viruses (influenzaviruses) designated A, B, and C, has a 3-day incubation period, and usually lasts for 3 to 10 days. "In addition, there is evidence from others, showing that IL-34 is significantly induced in influenza infected patients in an autocrine and paracrine fashion, supporting a role for IL-34 in the course of SARS-COV-2 viral infection." (PMID 34422917, 2021).
interstitial lung disease (2 papers, 2021 to 2025). A diverse group of lung diseases that affect the lung parenchyma. "Additionally, research has indicated that IL-34 is associated with respiratory diseases such as pneumonia and interstitial lung disease." (PMID 40176879, 2025). "Additionally, another study indicated that IL-34 levels are elevated in patients with systemic sclerosis and are strongly linked to the incidence and severity of interstitial lung disease." (PMID 40176879, 2025). "Additionally, serum IL-34 levels in patients with systemic sclerosis have been reported to increase with the severity of interstitial lung disease." (PMID 40176879, 2025).
Listeria infection (2 papers, 2019 to 2020). "In a Listeria monocytogenes infection model, CSF-1/IL-34 blockade or treatment with anti-CSF-1 alone increased susceptibility to bacterial infection, although to a lower degree than anti-TNF therapy." (PMID 33162994, 2020). "Furthermore, evaluation of IL34 and CSF1 blockade treatment during Listeria infection reveals no substantial safety concerns." (PMID 31552020, 2019).
liver cirrhosis (2 papers, 2016 to 2017). "The IL-34 significantly increased with the progression of fibrosis and was an independent marker for liver cirrhosis (odds ratio = 1.233, p = 0.006)." (PMID 29201774, 2017). "For the diagnosis of liver cirrhosis, the area under the curve (AUC) and sensitivity and specificity of IL-34 (0.87, 83.3, and 80.2% respectively) were superior to or comparable with the other serum biomarkers and fibrosis indexes." (PMID 29201774, 2017). "IL-34 was expressed mainly on the fibroblasts identified as α–SMA positive [liver cirrhosis (Stage 4) and advanced fibrosis (Stage 3)]." (PMID 27363523, 2016). "Using receiver-operating characteristic (ROC) analyses, the area under the curves (AUC) of IL-34 were 0.68 for significant fibrosis (≥Stage 2), 0.76 for advanced fibrosis (≥Stage 3), and 0.87 for liver cirrhosis (Stage 4)." (PMID 27363523, 2016). "For the diagnosis of liver cirrhosis (Stage 4), the AUC, sensitivity, and specificity of IL-34, which were 0.87, 83.3%, and 80.2%, respectively, were superior to or comparable with the other serum biomarkers and fibrosis indexes." (PMID 27363523, 2016). "We also stained the non-cancerous liver specimens obtained from patients with HCV infection, and IL-34 was expressed mainly on the fibroblasts [liver cirrhosis/Stage 4]." (PMID 27363523, 2016). "In multivariate analyses, IL-34 was an independent marker for liver cirrhosis (Stage 4) [odds ratio (OR) = 1.233, p = 0.006]." (PMID 27363523, 2016). "The AUC, sensitivity, and specificity of IL34-FS were, respectively, 0.86, 75.2%, and 85.0% for significant fibrosis (≥Stage 2); 0.88, 81.7%, and 79.4% for advanced fibrosis (≥Stage 3); 0.91, 83.3%, and 85.6% for liver cirrhosis (Stage 4)." (PMID 27363523, 2016).
lymphoma (2 papers, 2019 to 2022). A malignant (clonal) proliferation of B- lymphocytes or T- lymphocytes which involves the lymph nodes, bone marrow and/or extranodal sites. "M-CSF- and IL-34-targeted CAR T-cells were co-incubated with these engineered lymphoma cells and the viability of the latter was monitored daily for six days using luciferase assays." (PMID 35883636, 2022). "More interestingly, IL‐34+ patients showed shorter survival periods and higher number of macrophages in lymphoma tissues." (PMID 31417675, 2019). "The recruitment of monocytes is likely the first step for the higher macrophage density in the IL‐34+ lymphoma tissues." (PMID 31417675, 2019). "The recruitment of monocytes is likely the first step for the higher number of macrophages in the IL‐34+ DLBCL lymphoma tissues." (PMID 31417675, 2019). "In summary, our study raises the possibility that IL‐34 ectopically expressed recruits monocytes into lymphoma tissues of DLBCL by its stable migration‐inducing activity, which leads to the higher density of macrophages and the poor prognosis of patients." (PMID 31417675, 2019). "Our results raise the possibility that IL‐34 in lymphoma tissues of DLBCL patients recruits monocytes, leading to the higher number of macrophages in the tissues and poor prognosis of patients." (PMID 31417675, 2019). "Several lymphoma tissues showed a clear IL‐34 signal, and such signal was detectable in 36% of patients." (PMID 31417675, 2019). "In contrast, several lymphoma tissues showed a clear IL‐34 signal (right), and such signal was detectable in 35.6% (48/135) of lymphoma tissues of DLBCL patients." (PMID 31417675, 2019). "We analysed formalin‐fixed paraffin‐embedded lymphoma tissues of 135 DLBCL patients for the expression of IL‐34 and the number of macrophages, and the survival of these patients." (PMID 31417675, 2019). "Another noteworthy finding of this study was that the number of macrophages in lymphoma tissues of IL‐34+ DLBCL patients was significantly higher than that of IL‐34− patients." (PMID 31417675, 2019). "We therefore analysed the role of IL‐34 in diffuse large B‐cell lymphoma (DLBCL), the most common subtype of malignant lymphoma." (PMID 31417675, 2019). "All these lymphoma cell lines produced either M-CSF and/or IL-34, unlike either T47D or T47D FMS cells." (PMID 35883636, 2022). "In summary, our results raise the possibility that IL‐34 in the lymphoma tissues of DLBCL patients does not directly act on DLBCL cells but recruits monocytes, leading to the higher number of macrophages in the tissues and poor prognosis of patients." (PMID 31417675, 2019). "Our findings may suggest that IL‐34 is one such factor because IL‐34, which induces the migration of monocytic cells, is often expressed in the DLBCL lymphoma tissues." (PMID 31417675, 2019).
mesothelioma (2 papers, 2014 to 2021). A usually malignant and aggressive neoplasm of the mesothelium which is often associated with exposure to asbestos. "To obtain a suitable experimental system to study the CSF-1R function in mesothelioma cells, we analyzed the expression of CSF-1R and its ligands CSF-1 and IL-34 in a panel of mesothelioma cell lines and an untransformed mesothelial cell line immortalized by h-TERT (LP9)." (PMID 24722292, 2014). "Therefore, we investigated the involvement of the CSF-1R/CSF-1/IL-34 system in mediating the resistance of the mesothelioma cells to pemetrexed." (PMID 24722292, 2014). "Thus, targeting the IL-34, M-CSF and CSF-1R may represent a potential therapeutical approach to suppress both mesothelioma cells and pro-tumor macrophages." (PMID 34830817, 2021). "More recently, a chemoresistant phenotype of a CSF-1R+ population of mesothelioma cells, detected in primary cultures and MPM cell lines, resulted in being supported by the expression of both IL-34 and M-CSF ligands." (PMID 34830817, 2021). "Next, ELISA assay revealed that 7/7 mesothelioma cell lines secreted IL-34 and 6/7 MPM cell lines secreted CSF-1, with the levels of IL-34 being generally higher than those of CSF-1." (PMID 24722292, 2014).